TYRO3 (TYRO3 protein tyrosine kinase)
Diseases named in the same sentence as TYRO3 in open-access papers (continued):
Sharing a sentence is not in itself a finding about the gene and the disease.
cancer (84 papers, 2013 to 2026). A tumor composed of atypical neoplastic, often pleomorphic cells that invade other tissues. "The functional enrichment analysis of the modeled pathways of full-length and ICD of TYRO3 was able to identify unique pathways associated with various cellular processes including ones involved in the pathogenesis of cancer." (PMID 38703893, 2024). "Potential targets for cancer therapy include efferocytosis-related genes and pathways, such as phosphatidylserine, TYRO3, MerTK, indoleamine-2,3-dioxygenase 1, membrane-linked protein V, CD 47, TGF-β, and IL-10." (PMID 37853449, 2023). "Along with wildtype ProS1, these variants were added to both SCC-25 and MGH-U3 cancer cell lines which served as readouts for Tyro3 and Tyro3-dependent Erk kinase activation." (PMID 35518197, 2022). "Taken together, these studies suggest that overexpressed TYRO3 is associated with tumorigenesis, cancer progression, and metastasis, and is an effective drug target for cancer treatment." (PMID 34721022, 2021). "In HCC, both Axl and Tyro3 are aberrantly expressed in sorafenib-resistant cancer cells, and loss-of-function studies result in increased chemosensitivity." (PMID 34771611, 2021). "Downstream of AXL and TYRO3, numerous intracellular signalling pathways have been associated with cancer progression and drug resistance." (PMID 33059733, 2020). "The TAM subfamily (Tyro3, Axl, MerTK) of receptor tyrosine kinases are implicated in several cancers, where they have been shown to support primary tumorigenesis as well as secondary resistance to cancer therapies." (PMID 31766614, 2019). "The TAM receptor tyrosine kinases (Tyro-3, Axl and Mer) have been widely implicated in the development of cancer and other diseases; thus, they have become therapeutic targets of interest." (PMID 25310149, 2014). "Conversely, over-expression or aberrant activation of Tyro3, Axl, or Mer (gene name Mertk) is associated with the development, progression, and metastasis of cancers." (PMID 25265470, 2014). "TYRO3 mutations have been also noted in human malignancies, but the function of these mutations has not been proven to elucidate the potential significance of these mutations in cancer." (PMID 36454644, 2023). "Although further studies are needed to determine the exact mechanism underlying G-749-induced TYRO3 fragmentation, our findings suggest that the regulation of TYRO3 protein turnover by G-749 may be a promising novel cancer treatment strategy." (PMID 34721022, 2021). "The TAM (Tyro3, Axl, MerTK) subfamily of receptor tyrosine kinases (RTKs) and their ligands, Gas6 and protein S (ProS1), are implicated in tumorigenesis and chemoresistance in various cancers." (PMID 32664510, 2020). "Overall, these findings suggest that AXL/TYRO3 overexpression, frequently seen in cancers, promotes the loss of RIPK3 expression and escape from necroptosis, which may be reversed upon inhibition of these kinases." (PMID 30157175, 2018). "Furthermore, Tyro3 has also been implicated as a mediator of resistance to anti-cancer agents." (PMID 31766614, 2019). "Previous BrM protein profiling revealed that AXL, a member of the TAM (TYRO3, AXL, MER) receptor tyrosine kinase family implicated in oncogenesis and metastasis of many cancer types is elevated in BrM cells." (PMID 41356185, 2026). "Axl, a member of the receptor tyrosine kinase family comprised of Tyro3, Axl, and MerTK, is a promising cancer therapeutic target actively under clinical investigation." (PMID 40539073, 2025). "Gene groups linked to efferocytosis, including Tyro3, Axl, MerTK, Gas6, BAI-1, CX3CL1, CD31, CD47, Rac1, and the TIM family, represent significant targets for prospective cancer therapies." (PMID 39911848, 2025). "The IL-6/STAT3 signaling pathway and TYRO3 collectively involve cancer cell survival, proliferation, and resistance to chemotherapeutic agents." (PMID 38431573, 2024).
cancer (continued). "To rule out that reduced efferocytosis activity in KO macrophages was due to a defect in the recognition of phosphatidylserine on apoptotic cancer cells by TAMs, we measured mRNA levels of receptor tyrosine kinase family members such as MerTK, Tyro3, and Axl." (PMID 38308188, 2024). "TYRO3, a receptor tyrosine kinase expressed in cancer cells, suppressed T-cell mediated ferroptosis by upregulating NRF2 pathway activation." (PMID 37612411, 2023). "While the roles of MER and AXL in these cancer processes have been well described, less is known about the roles of TYRO3." (PMID 36454644, 2023). "Anti-TYRO3 antibodies inhibited the cancer progression or metastasis of colon cancer and melanoma cells." (PMID 37475048, 2023). "The survival follow-up information of CRC patients and TYRO3 expression level in cancer tissues were utilized to conduct relevant subgroup analysis depending on clinicopathological indicators." (PMID 37116196, 2023). "For the last selected gene set the associated predicted networks were mainly associated to cancer and in one of those emerged the TAM family of RTKs (TYRO3, AXL, MER) and in particular a slight AXL up-modulation in the gene expression." (PMID 37041632, 2023). "We have shown that ProS1 is a preferred ligand for Tyro3 over Gas6 in human cancer cells expressing both Tyro3 and Axl receptors, as well as identified Tyro3 signaling pathways that progress the cell cycle and support survival in cancer cells." (PMID 35518197, 2022). "•The first LG domain (LG1) of protein S is essential for activation of Tyro3 and downstream signalling in human cancer cells." (PMID 35518197, 2022). "Upregulation of the Mer receptor tyrosine kinase (MERTK), which is a member of the Tyro3-Axl-MERTK (TAM) family, is associated with a poor prognosis of many cancers." (PMID 33562150, 2021). "TYRO3 is overexpressed in various cancers and is attracting attention as a potential cancer therapeutic target." (PMID 34721022, 2021). "In particular, numerous studies have reported that the PI3K/AKT pathway, a downstream signaling pathway of TYRO3, plays an important role in cancer cells." (PMID 34721022, 2021). "Tumor-secreted protein S (ProS1) activates a Tyro3-Erk signaling axis and protects cancer cells from apoptosis, and thus supports cancer cell survival." (PMID 33947134, 2021). "To identify the potential downstream component of the GAS6/MER pathway, we compared the expression of MER, AXL, and TYRO3 among various human cancer cell lines including HeLa, DU145, THP-1, RKO, SKM1, A549, OCI-LY3, G361, and HL60." (PMID 32042425, 2020). "Although roles for AXL and MER in cancer progression have been well-described, less is known about the role of TYRO3." (PMID 32018224, 2020). "Previous literature has shown that TYRO3 is significantly increased in various cancers, and it promotes cancer cell proliferation and metastasis and enhances drug resistance, and thus is a potential therapeutic target." (PMID 32908453, 2020). "In general, much less is known about TYRO3, including the role it plays in cancer development and progression." (PMID 33059733, 2020). "Our data show that ProS1 is an active and functional ligand for Tyro3 in human cancer cells, rapidly stimulating its phosphorylation as well as Erk, moreover, predominating over Gas6 as a ligand for this specific RTK." (PMID 31766614, 2019). "In the present study, we have investigated the expression of Tyro3 in a variety of human cancer cell lines and revealed that the ligand selectivity of Tyro3 is a factor of TAM expression profile in cancer cells." (PMID 31766614, 2019). "The same profile of Tyro3 activation by ProS1 was also observed in several of the other cancer cell lines expressing Tyro3." (PMID 31766614, 2019). "Here, we have focused on the specific role of Tyro3 expression and activation in cancers and attempted to delineate the downstream signalling pathways activated by ProS1-Tyro3 as compared to Gas6-Axl." (PMID 31766614, 2019).
cancer (continued). "Having shown that exogenous recombinant ProS1 activates Tyro3 and downstream Erk signalling in human cancer cells, we also investigated the effect of endogenous ProS1 secreted by human cancer cells as a functional Tyro3 ligand." (PMID 31766614, 2019). "Given the preclinical evidence of the involvement of TYRO3 in cancer, it is important to develop potent small inhibitors or monoclonal antibodies specific against this tyrosine kinase receptor." (PMID 30765874, 2019). "Growth arrest-specific protein 6 (Gas6), one of the endogenous ligands of TAM receptors (Tyro3, Axl, and Mertk), is confirmed to have beneficial functions in hemostasis, inflammation, and cancer growth." (PMID 31263416, 2019). "Our results showed that ProS1 naturally secreted from cancer cells is functional in being able to activate Tyro3 and Erk kinase downstream to the same extent as recombinant ProS1." (PMID 31766614, 2019). "These novel data shed further light on the currently poorly understood roles of both Tyro3 and ProS1 in tumorigenesis and highlight Tyro3 as a novel cancer therapeutic target in addition to Axl." (PMID 31766614, 2019). "While numerous studies have described signalling pathways downstream of Axl and MerTK and the changes following stimulation with TAM ligands, relatively few studies have directly assessed signalling pathways downstream of Tyro3, particularly in cancers." (PMID 31766614, 2019). "Relatively little is known about the oncogenic role of Tyro3, including its ligand selectivity and signalling in cancer cells." (PMID 31766614, 2019). "At protein level, Tyro3 was the most ubiquitously expressed of the three TAM receptors in the cancer cell lines tested." (PMID 31766614, 2019). "Inhibition studies have also revealed a role for Tyro3 in metastasis, reflected in decreased cancer cell migration and invasion." (PMID 31766614, 2019). "Recent studies revealed roles for TYRO3 in cancer and suggest TYRO3 as a therapeutic target in this context." (PMID 30501104, 2018). "Inhibition of TYRO3 increased sensitivity to cytotoxic chemotherapies in a variety of cancer cell lines in cell culture models." (PMID 30501104, 2018). "Tyro3 and Axl protein levels are undetectable in normal thyroid cells, whereas they show significant expression in cancer cell lines, which was also confirmed in RT-polymerase chain reaction (RT-PCR) experiments." (PMID 28333143, 2017). "The TAM family of proto-oncogenic receptor protein tyrosine kinases, comprising of TYRO3, AXL, and MERTK, is implicated in many human cancers." (PMID 28118606, 2017). "Increased expression of Epiregulin has been shown to be a biomarker for several cancers Axl belongs to the TAM (Tyro-3, Axl and Mer) family of receptor tyrosine kinases." (PMID 26036314, 2015). "A pathway that is implicated in dormancy maintenance across multiple cancer types in bone is GAS6 expressed by osteoblast lineage cells and also breast cancer cells, binding to TYRO3, AXL or MER (TAM) tyrosine kinase receptors, although the type of receptor expressed varies across cancer types." (PMID 41091336, 2025). "Inhibiting TYRO3 expression could effectively reverse drug resistance and down-regulate the proliferation and migration ability of cancer cells." (PMID 37116196, 2023). "However, studies suggest that TYRO3 expression is increased in several types of cancers, although its baseline expression in normal tissues is relatively low." (PMID 36454644, 2023). "AXL is a member of the TAM (TYRO3, AXL, and MERTK) receptor tyrosine kinases family (RTKs), and its abnormal expression has been linked to clinicopathological features and poor prognosis of cancer patients." (PMID 37328828, 2023). "Additionally, targeting TYRO3 can down-regulate ENO1 to inhibit the EMT process by interfering with energy metabolism in cancer cells." (PMID 37116196, 2023). "TYRO3 expression was detected in the cancer tissues of 120 CRC patients using the IHC test." (PMID 37116196, 2023).
cancer (continued). "The inhibition of TYRO3 expression could effectively reverse its drug resistance and down-regulate cancer cell proliferation and migration." (PMID 37116196, 2023). "Here, we show that TAM receptors MERTK and TYRO3 exert reciprocal effects in osteoblast biology: Osteoblast-targeted deletion of MERTK promotes increased bone mass in healthy mice and mice with cancer-induced bone loss, whereas knockout of TYRO3 in osteoblasts shows the opposite phenotype." (PMID 36509738, 2022). "For instance, Tyro3 was shown to contribute to the resistance to ICI treatment through inhibition of ferroptosis that is required for T cell‐mediated cancer cell killing, providing a combination therapy of a Tyro3 inhibitor and ICIs to treat these types of resistant patients." (PMID 35588146, 2022). "While AXL and MER have been thoroughly investigated, the role of TYRO3 in cancer development remains unknown." (PMID 34721022, 2021). "However, a growing number of reports have shown that TYRO3 is overexpressed in various cancers with poor prognoses, and it has been proposed as a potential target for cancer treatment." (PMID 34721022, 2021). "Notably, emerging evidence has shown that TYRO3 has an important role in cell proliferation, invasion, and chemoresistance in various types of cancers." (PMID 32018224, 2020). "As Gal-3 is considered as a biomarker for many cancers, often showing increased expression, knowledge on the molecular mechanisms by which it affects cancer cells, e.g. through Tyro3 activation as shown here, it can offer a novel avenue for cancer therapeutics and/or diagnostics." (PMID 32664510, 2020). "These novel findings demonstrate that Tyro3 is also linked to cancer cell survival as well as proliferation through the actions of ProS1, given that ProS1 only activates Tyro3 and not Axl." (PMID 31766614, 2019). "Tyro3 showed widespread protein and mRNA expression in a variety of human cancer cell lines." (PMID 31766614, 2019). "Additionally, the selectivity test against other kinases also reveals a high affinity of R5 toward ABL1 and Tyro3 kinases, emphasizing its promising potential for the treatment of malignant tumors." (PMID 32117858, 2019). "However, relatively little is known about Tyro3 in terms of its cancer expression profile, mechanisms of activation and cellular signalling and functional roles." (PMID 31766614, 2019). "Other pathways were identified as regulated in both studies, including proliferation, survival/growth and apoptosis, suggesting possible roles for TYRO3 in these processes and the existence of general features relating to TYRO3 activity in different cancer types." (PMID 30765874, 2019). "Furthermore, we have investigated the signalling pathways activated specifically via Tyro3 and the functional effects of Tyro3 signalling in cancer cells." (PMID 31766614, 2019). "TYRO3 is not only abnormally expressed in cancer cells, it is also activated." (PMID 30501104, 2018). "Moreover, high AXL/TYRO3 levels are potential predictors/biomarkers for loss of RIPK3 expression and necroptosis resistance in cancer." (PMID 30157175, 2018). "Through Akt/NF-κB signalling, Tyro3 exerts prosurvival effects and promotes cancer cell survival." (PMID 28333143, 2017). "Tyro3, Axl, and Mertk (TAMs) are a family of three conserved receptor tyrosine kinases that have pleiotropic roles in innate immunity and homeostasis and when overexpressed in cancer cells can drive tumorigenesis." (PMID 27595981, 2016). "Although the signal transduction pathways of TYRO3 are not fully explored, its overexpression and activation have been linked to enhanced cell survival, proliferation, metastasis, and therapy resistance in various cancers." (PMID 39924521, 2025). "Except for BAI1, CD31, and MerTK, the enhanced expression of Axl, Tyro3, Gas6, MFGE8, Stab2, Tim-4, CX3CL1, IDO1, Rac1, and PD-L1 was associated with decreased sensitivity to many drugs, which may partially explain the resistance to chemotherapy in cancers." (PMID 36059952, 2022).
cancer (continued). "In addition, TYRO3 mutations have been identified in various cancers, and none have been reported to be associated with cancer development." (PMID 34721022, 2021). "However, some cancer type-specific features may fine-tune TYRO3-mediated signalling pathways and their outcomes." (PMID 30765874, 2019). "TYRO3, a member of the TYRO3, AXL, and MerTK (TAM) receptor tyrosine kinase (RTK) family, is upregulated in various cancers." (PMID 40299539, 2025). "Sitravatinib, a receptor kinase inhibitor targeting TYRO3, AXL, MERTK, and VEGFR2, is being studied in combination with nivolumab for various cancers." (PMID 39924521, 2025). "Subsequently, we analysed the expression levels of these genes across 33 types of cancer and found that AXL, MERTK, TYRO3, CD24, HAVCR2 and CD47 exhibited higher expression levels, while TIMD4 and HAVCR1 showed relatively lower expression." (PMID 40576208, 2025). "MERTK is a member of the TAM family (TYRO3, AXL, MERTK) of receptor tyrosine kinases and is aberrantly or ectopically expressed in a spectrum of human cancers, where it functions to promote tumor cell survival, metastasis and chemoresistance." (PMID 39199601, 2024). "Mer‐tyrosine kinase (MERTK), a member of the AXL, TYRO3, and MERTK (TAM) family, is one of the promising targets for cancer treatment." (PMID 39635932, 2024). "The TAM (TYRO3, AXL, MerTK) subfamily is prominent in multiple cancer types resistant to various therapeutic agents, such as targeted and conventional chemotherapy." (PMID 37116196, 2023). "It is expressed in many human tissues and different types of cancers, and by binding to its three receptors (AXL, MERTK, TYRO3) plays a role in biological processes, i.e., proliferation, apoptosis, migration, and survival." (PMID 35626092, 2022). "The receptor tyrosine kinases Tyro3, Axl and MerTK—belonging to the TAM family—exert a large impact on various aspects of cancer biology." (PMID 34771611, 2021). "At present it is not well known how expression of AXL and TYRO3 is regulated; given the emerging role of TAM RTKs in cancer and drug response however, this is an area of active research." (PMID 33059733, 2020). "As the roles of both Tyro3 RTK and ProS1 in cancer cell biology remained to be characterised, the Tyro3-activating abilities of both TAM ligands were compared." (PMID 31766614, 2019). "The TAM receptors Tyro3, AXL, and MERTK are oncogenic drivers that promote survival, chemoresistance, and motility of cancer cells." (PMID 29382817, 2018). "The overexpression and hyperactivation of members of the TAM family of receptor tyrosine kinases – comprising TYRO3, AXL and MERTK is documented in many cancers." (PMID 28118606, 2017). "The receptor tyrosine kinases (RTKs) TYRO3, AXL and MERTK (TAM) have well-described oncogenic functions in a number of cancers." (PMID 28727830, 2017). "Deregulation of the TAM (TYRO3, AXL, and MERTK) family of receptor tyrosine kinases (RTKs) has recently been demonstrated to predominately promote survival and chemoresistance of cancer cells." (PMID 28034848, 2017). "There was also a trend toward decreased CERES scores for the TAM-family kinase TYRO3 in EWS compared to all other cancer cell lines, but the difference was not statistically significant (p = 0.07)." (PMID 39199601, 2024). "Regulation of TYRO3 in CRC by specific non-coding RNA molecules has recently been documented, and these studies also highlight the clear relationship between TYRO3 overexpression and cancer." (PMID 37296477, 2023). "In summary, MERTK and TYRO3 represent potent regulators of bone homeostasis with cell-type specific functions and MERTK blockade represents an osteoanabolic therapy with implications in cancer and beyond." (PMID 36509738, 2022). "Despite the wealth of literature and date implicating the role of TYRO3 in cancers, there are no studies that have investigated TYRO3 therapeutic potential in combination with radiation treatment." (PMID 35955805, 2022).